NAMPT (nicotinamide phosphoribosyltransferase)
Diseases named in the same sentence as NAMPT in open-access papers (continued):
Sharing a sentence is not in itself a finding about the gene and the disease.
cancer (continued). "Overexpression of NAMPT has been shown in many cancer types and inhibitors of NAMPT have been shown to prevent cancer growth." (PMID 40076592, 2025). "Here, we summarize the current state of the science on NAMPT inhibitor resistance in cancer, focusing on altered regulation of compensatory NAD+ synthesis pathways, drug target mutations, metabolic adaptations, and drug transporters." (PMID 40342733, 2025). "NAMPT-driven deregulation of metabolism in cancer cells represents a vulnerability that can be therapeutically exploited to benefit tumor patients." (PMID 40775221, 2025). "So, NAMPT inhibition, with the subsequent decline of NAD + levels, causes sensitisation of cancer cells to oxidative damage and initiation of cell death." (PMID 40085284, 2025). "The impact of eNAMPT silencing on cancer cell migration and invasion was investigated, demonstrating that NAMPT suppression mitigated these capabilities, which are typically enhanced by M2 macrophage influence." (PMID 40083697, 2025). "Preclinical work in a variety of cancer models has demonstrated the emergence of resistance to multiple NAMPT inhibitors through several recurrent mechanisms." (PMID 40342733, 2025). "This review summarizes the multiple roles of NAMPT in both physiological and pathological states, particularly in cellular stress, aging, metabolic disorders, and cancer." (PMID 40775221, 2025). "Of note, multiple studies that profiled cancer cells to identify those with sensitivity to NAMPT inhibition found that cells with lower NAMPT expression demonstrated increased sensitivity." (PMID 40526635, 2025). "Cancers dependent on the NAD+ salvage pathway and deficient in NAPRT are sensitive to NAMPT inhibitors, while cancers dependent on the Preiss–Handler pathway with high NAPRT expression are resistant." (PMID 39272943, 2024). "In future, detailed analysis of the correlation between olaparib resistance and intracellular NAD+ levels and/or NAMPT expression should be performed using samples from cancer patients in which olaparib resistance has been induced." (PMID 38625917, 2024). "Our work raises important questions about the link between PAK4 and NAMPT inhibition in cell growth, emphasizing the need for further research to identify the most effective inhibitors in cancer treatment." (PMID 39337621, 2024). "TCGA analysis indicated that NAMPT expression is upregulated in various cancer types compared to normal tissues." (PMID 38308188, 2024). "This sponging leads to the subsequent upregulation of BMI1, KRAS, AKT3, KLF12, and NAMPT, along with several other cancer-promoting genes, thus promoting a more aggressive phenotype." (PMID 39039064, 2024). "The key enzyme that maintains NAD levels in cancer cells is nicotinamide phosphoribosyltransferase (NAMPT)." (PMID 38893173, 2024). "Surprisingly,with a value of 362 nTPM (normalized transcripts per million), theU87MG cancer cell line expressed the highest NAMPT mRNA level of thewhole series." (PMID 38924492, 2024). "Considering these findings, the inhibition of NAMPT, including its enzymatic activity and Visfatin effects, has been suggested as a potential therapeutic target for cancer treatment." (PMID 39452130, 2024). "NAMPT inhibitors have demonstrated significant anticancer activity in both in vitro and in vivo cancer models." (PMID 39272943, 2024). "NAMPT is overexpressed in various cancers due to the need to meet increased energy demands, driving cellular metabolism and responses to NAD+ depletion." (PMID 39272943, 2024). "Interest in NAMPT as an anti-cancer target has led to the development of several NAMPT-specific inhibitors, including FK-866/APO-866, GNE-617, GNE-618, and CHS-828." (PMID 38424218, 2024). "Consistent with TCGA data, we experimentally examined the expression of NAMPT and PD-L1 in 11 cell lines from different cancers and found that the expression levels of the two proteins were negatively correlated." (PMID 38448544, 2024).
cancer (continued). "Given that the anti-tumor effect of NAMPT inhibitors can be reversed by NA supplemented in cell culture medium in NAPRT-dependent cancers." (PMID 38424218, 2024). "CHS828 is an effective NAMPT inhibitor that has been used in clinical trials for cancer treatment, but further development was halted due to toxicity and poor effectiveness." (PMID 39513038, 2024). "Here, we report a previously uncharacterised mechanism whereby constitutive TWEAK/Fn14 signalling induces the activity of an oncogenic SE targeting NAMPT, a key regulator of cancer cell metabolism, in TNBCs." (PMID 38965263, 2024). "These enzymes have been shown to supply cancer cells with enough NAD+ to overcome cell death due to NAD+ depletion through NAMPT inhibition." (PMID 38399441, 2024). "An extensive study that later explored NAMPT and NAPRT expression patterns across normal human tissues and cancer cell lines found that both NAMPT and NAPRT transcripts were widely expressed across normal human tissues." (PMID 38396769, 2024). "In humans, the NAM salvage pathway is a major source of NAD+ synthesis in humans, and NAMPT has been considered as a promising target for cancer treatment due to its role in providing NAD+ for tumor growth." (PMID 38429435, 2024). "NAMPT influences metabolic disorders and cancer by modulating oxidative stress, apoptosis, lipid metabolism, inflammation, and insulin resistance." (PMID 39272943, 2024). "Under QPRT inhibition, NAD+ synthesis is secured by the activation of a salvage pathway, often preferred by cancer cells, in which nicotinamide is converted by nicotinamide phosphoribosyltransferase (NAMPT) into NAD+." (PMID 39337426, 2024). "NAMPT inhibitor holds clinical potential not only as a promising cancer treatment but also as a means of protection against chemotherapy-induced-peripheral-neuropathy (CIPN)." (PMID 37771778, 2023). "We also reveal that in mice, dietary niacin counteracts the efficacy of targeting NAMPT in those cancers." (PMID 38092728, 2023). "To this aim, we performed a bioinformatic analysis to evaluate the expression levels of TRF2 and NAMPT in a number of publicly available cancer genomic datasets from the cBioPortal platform." (PMID 37858982, 2023). "The search for new NAMPT inhibitors is motivated by the need to identify novel drugs that counter cancer progression and thereby increase patient life expectancy and quality of life, a goal of a high priority." (PMID 36838885, 2023). "Analysis of the DepMap dataset revealed that NAMPT-KO effects in SCLC were more robust than in pan-cancer or NSCLC groups but similar to the AML group." (PMID 38092728, 2023). "KPT-9274 is a dual NAMPT/p21-activated kinase 4 (PAK4)/inhibitor that decreases the NAD+/NADH ratio in cancer cells, inhibiting tumor growth in sarcoma mice models and RCC." (PMID 37046703, 2023). "FK866 is a tight-binding, competitive inhibitor of NAMPT 29; therefore, we compared A4276 with FK866 to gain insights into the mechanism underlying A4276's superior selectivity against NAPRT-negative cancer cell lines." (PMID 37771778, 2023). "The involvement of NAMPT in multiple key biochemical processes is the foundation of inhibiting cancer cell NAMPT activities as a potential therapeutic strategy for AML treatment." (PMID 37746249, 2023). "Nicotinamide phosphoribosyl transferase (NAMPT) played a crucial role in cancer cell metabolism, often overexpressed in tumor tissues and was an effective target for antitumor treatments." (PMID 37065499, 2023). "In conclusion, a variety of downstream protein regulatory pathways that collectively make up a systemic regulatory network in CCA cell growth and invasion are linked to energy metabolism through NAMPT/NAD+ and are the potential targets for cancer therapeutics." (PMID 36899911, 2023). "NAMPT is the rate-limiting enzyme in the NAD biosynthetic pathway, showing an overexpression in many cancer cells associated with poor prognosis." (PMID 36900207, 2023).
cancer (continued). "Collectively, the structural data and NAMPT enzyme activity assays support the notion that A4276 confers a growth-inhibitory effect on cancer cells with decreased NAPRT levels by directly binding to and reversibly inhibiting the activity of NAMPT." (PMID 37771778, 2023). "Forkhead box O1 (FOXO1) is known as a cancer suppressor and it is able to suppress the NAMPT expression." (PMID 37175631, 2023). "Taken together, these discoveries offer a rationale for focusing on NAMPT/NAPRT as an innovative approach to trigger metabolic impairment resulting in cancer cell death." (PMID 38116009, 2023). "NAMPT overexpression promotes the progression of glioblastoma, melanoma, colon, breast cancer, and other cancer types." (PMID 37037593, 2023). "Since NAD+ levels are important in determining the fate of a cancer cell to surviving a therapy, we examined if the protein NAMPT, the rate-limiting enzyme in NAD biosynthesis, played a role in a cancer cell line resistance to metformin treatment." (PMID 37583931, 2023). "NAMPT suppression reversed the capability of cancer cells to dedifferentiate and potentially decreased the CSC load in metastatic prostate cancer." (PMID 38116009, 2023). "Dual inhibition of NRK1 and NAMPT result in more effective cancer suppression in vivo through inhibition of NAD+." (PMID 37175631, 2023). "NAMPT enhances cellular proliferation and tips the balance toward cell survival following a genotoxic insult; moreover, NAMPT is considered a molecular link among metabolism, inflammation, and cancer." (PMID 36980589, 2023). "In particular, comparative analyses with FK866, a relatively well-studied competitive NAMPT inhibitor in cancer and axonopathy, revealed the mechanism behind the A4276 efficacy." (PMID 37771778, 2023). "As NAMPT and NAPRT are the rate-limiting enzymes of the two NAD+ biosynthetic pathways, neoplastic depletion of NAPRT can serve as a biomarker of NAMPT inhibitor-sensitive cancer." (PMID 37771778, 2023). "This is consistent with the importance of NAMPT in supporting cancer cell metabolism, DNA repair, and proliferation, and in shaping the tumor microenvironment." (PMID 36980589, 2023). "Background/aims: The implications of extracellular nicotinamide phosphoribosyltransferase (eNAMPT), a cancer metabokine, in colonic polyps remain uncertain." (PMID 36980589, 2023). "Resistance to medication treatment of cancer cells is affected by NAMPT inhibitors in such way that therapeutic decline is prolonged." (PMID 36900207, 2023). "Inhibiting NAMPT to suppress NAD+ production is a successful approach for modifying cancer cell metabolism and decreasing ATP levels." (PMID 38116009, 2023). "The treatment of newly diagnosed cancer patients who regularly engage in physical activity, in our opinion, should place special focus on inhibiting iNAMPT or NAMPT expression in general." (PMID 37954044, 2023). "Together with the growing potential of NAMPT as a therapeutic target for cancer treatment, numerous NAMPT inhibitors have been developed 8-11." (PMID 37771778, 2023). "In this study, we developed and analyzed a novel NAMPT inhibitor, A4276, which exhibits remarkable anti-tumor activity against NAPRT-deficient EMT-subtype cancers." (PMID 37771778, 2023). "Data obtained from databases indicate that both normal and various types of cancer ovarian cells express NAMPT." (PMID 36658296, 2023). "Efficacy of NAMPT inhibitors in the treatment of cancer aroused the interest of oncological research for a long time." (PMID 37858982, 2023). "Consistently, NAMPT and SIRT1 levels have been seen to rise in HCC and other cancers, a condition linked to a bad prognosis for those who have the disease." (PMID 36899911, 2023). "Nicotinamide phosphoribosyltransferase (NAMPT) plays a major role in NAD biosynthesis in many cancers and is an attractive potential cancer target." (PMID 38092728, 2023).
cancer (continued). "Several enzymes involved in anabolic NAD+ pathways, such as nicotinamide phosphoribosyltransferase (NAMPT), have been heavily implicated in cancer progression and severity." (PMID 37842241, 2023). "It has been shown that mycoplasma contributes to host NAD+ biosynthesis, and experimentally, mycoplasma plays a role similar to that of resistance to NAMPT inhibitors in cancer cells and xenograft tumors." (PMID 37447179, 2023). "The expression of NAMPT is up-regulated in TANs in several cancer and the inhibition of NAMPT effectively suppresses SIRT1 signaling." (PMID 37679744, 2023). "In this regard, Thongon and colleagues evaluated the mechanisms of cancer cell resistance to nicotinamide phosphoribosyltransferase (NAMPT), the rate-limiting enzyme in NAD+ biosynthesis from nicotinamide." (PMID 37876966, 2023). "Since NAMPT plays an essential role in NAD+ replenishment, we explore how NAMPT levels can affect cancer susceptibility to metformin." (PMID 37583931, 2023). "The relative quantity (RQ) of NAMPT mRNA in non-cancer epithelial ovarian cells (HOSEpiC) was higher than that in granulosa ovarian cells (HGrC1) by 3.45-fold (***P < 0.001)." (PMID 36658296, 2023). "On the other hand, NAD+ supply of cancer that lack NAPRT expression is primarily dependent on NAMPT." (PMID 37175631, 2023). "The findings suggest that STF-31 has a dual function and that the inhibitory effect is concentration-dependent, so a number of cancer cells studied appear to be more sensitive to its lethal effects as a given NAMPT inhibitor." (PMID 36160449, 2022). "Emerging evidences have shown that NAMPT is overexpressed in a broad range of tumor cells, and it holds great promise to identify NAMPT inhibitors as potential therapies for cancers." (PMID 36615364, 2022). "In a number of cancer models, crosstalk between oncogenic signaling pathways and NAMPT has been documented." (PMID 36160449, 2022). "NAMPT has drawn considerable interest in the fields of metabolism, senescence, immune response, and cancer." (PMID 36615364, 2022). "Modulation of vascular endothelial cells determines cancer progression, and emerging experimental results suggest that NAMPT plays pivotal roles in this process." (PMID 35565188, 2022). "NAPRT, the rate-limiting enzyme of the Preiss–Handler NAD biosynthetic pathway, has emerged as a key biomarker for the clinical success of NAMPT inhibitors in cancer treatment." (PMID 35890155, 2022). "Our best candidates, compound 8 and compound 19, were able to restore the sensitivity of NAPRT-expressing cancer cells to NAMPT inhibitors through NAPRT inhibition." (PMID 35890147, 2022). "NAMPT is an attractive target in cancer therapy, and the development of NAMPT inhibitors represents a promising therapeutic approach." (PMID 36615364, 2022). "Several previously identified NAMPT inhibitors have shown efficacy in cancer models, including ovarian, colorectal, prostate, pancreatic, and non-small cell lung cancers, neuroblastoma, and fibrosarcoma." (PMID 35906622, 2022). "In recent years, the concentrations of circulating NAMPT have been widely studied in many types of cancers, metabolic conditions and chronic inflammatory diseases." (PMID 36443772, 2022). "QPRT is upregulated in cancer cells, and this upregulation is resistant to inhibitors of nicotinamide phosphoribosyltransferase (NAMPT), the rate-limiting enzyme of the NAD + salvage pathway." (PMID 35251175, 2022). "NAMPT knockdown led to an increase in drug sensitivity in cancer cells via the upregulation of multidrug resistance 1 (MDR1) as well as the increased p65 activation determined by nuclear localization." (PMID 35565188, 2022). "Compared to traditional small-molecule NAMPT inhibitors, antibody–drug conjugates (ADCs) can selectively target cancer cells through antibodies binding to cancer-specific cell surface markers, thereby sparing normal cells from systemic NAD depletion." (PMID 35903330, 2022).
cancer (continued). "NAMPT was observed to be overexpressed in a broad range of malignant tumors and to modulate cancer cell proliferation, metastasis, and induction of angiogenesis." (PMID 36556252, 2022). "Targeting NAMPT has been proposed as an anticancer strategy, and several NAMPT-selective inhibitors have been uncovered to significantly block NAMPT’s function in tumor cells as well as the attenuation of cancer progression." (PMID 35565188, 2022). "We envision that these ROS-activated NAMPT inhibitors would target cancer cells with high levels of ROS." (PMID 36615364, 2022). "Contrarily, other studies demonstrated an increased sensitivity of cancer cells with IDH mutations to several drugs, including alkylating agents, inhibitors of nicotinamide phosphoribosyltransferase (NAMPT), and inhibitors of poly ADP ribose polymerase (PARP)." (PMID 35740380, 2022). "Some research reported that SIRT6 specifically boosts NAMPT’s enzymatic activity through direct protein deacetylation to shield cancer cells from oxidative stress." (PMID 36160449, 2022). "The data of an analysis using tissue array from oral squamous cell carcinoma indicated the upregulation of NAMPT in cancer." (PMID 35565188, 2022). "In multiple cancer models, NAMPT inhibition was observed to decrease phosphorylation of ERK1/2, and NAMPT inhibitors and ERK1/2 blockers together increased cell death." (PMID 36160449, 2022). "Earlier studies have reported that FK866 is a NAMPT inhibitor and controls cancer progression by a downregulation of TNFα, IL-6 expressions, CXCR4." (PMID 36497496, 2022). "We demonstrated that the NAPRT inhibitor 2-hydroxynicotinic acid (2-HNA) cooperates with the NAMPT inhibitor FK866 in killing NAPRT-proficient cancer cells that were otherwise insensitive to FK866 alone." (PMID 35890147, 2022). "Accumulat ed data of in silico analyses from clinical cancer databases and the literature demonstrate NAMPT expression in many cancer types." (PMID 35565188, 2022). "Some studies have shown that NAMPT is a cancer-related factor and plays a vital role in the development and metastasis of tumors along with some immune-related substances." (PMID 35906622, 2022). "The lentivirus-mediated NAMPT knockdown or NAMPT inhibitor FK866 abolished cancer cell growth and induced cell apoptosis through the upregulation of caspase-3." (PMID 35565188, 2022). "Previous studies mainly focus on the anti-cancer functions of NAMPT inhibitors, while their potential neuroprotective effect has been recently highlighted." (PMID 35903330, 2022). "Lowering specific NAD+ precursors in the diet, silencing or inhibiting NAPRT in cancer cells or depleting the gut microbiota using antibiotics are all potential avenues for optimizing the activity of NAMPT inhibitors in hematological malignancies." (PMID 35396381, 2022). "NAMPT, the rate-limiting enzyme of this pathway, has been identified as an oncogene in some cancer types." (PMID 36078035, 2022). "The rate-limiting enzyme of this pathway, NAMPT, has been identified as an oncogene in some cancer types." (PMID 36078035, 2022). "NAMPT inhibitors have also been developed as payloads of antibody-drug conjugates (ADCs), which can selectively deliver NAMPT inhibitors to the targeted cancer cells." (PMID 36615364, 2022). "Increased NAMPT activity was observed in several human cancers, and NAMPT inhibition by drugs is promising as a cancer treatment." (PMID 36139711, 2022). "As the key rate-limiting enzyme in the salvage pathway of NAD synthesis, NAMPT has recently been shown to be a promoter of cancer." (PMID 35515130, 2022). "Lastly, our results support a novel finding to consider NAMPT itself a proto-oncogene in cancer driving cellular transformation." (PMID 35272691, 2022). "CHS828 was examined in a clinical trail in 1999, but it wasn’t until 2008 that Olesen’s research demonstrated that the compound can block NAMPT and kill cancer cells primarily by way of depleting NAD." (PMID 36160449, 2022).